IL6 (interleukin 6)
Diseases named in the same sentence as IL6 in open-access papers (continued):
Sharing a sentence is not in itself a finding about the gene and the disease.
Thrombocytopenia (continued). "The absence of thrombocytopenia, increase of serum IL-6, serum vascular endothelial growth factor, serum alkaline phosphatase, or adrenal involvement may lower the possibility of TAFRO syndrome." (PMID 39156319, 2024). "As with neutropenia, the exact mechanism by which tocilizumab induces thrombocytopenia is not clearly elucidated, but the hypothesis points to the role of IL-6 in increasing platelet levels during inflammation." (PMID 36091800, 2022). "Some parameters for which an unfavorable course of the disease has been described are absolute neutrophilia, thrombocytopenia, hypoalbuminemia, the elevation of liver enzymes, creatinine and nonspecific inflammatory markers such as C-reactive protein (CRP) and Interleukin 6 (IL-6)." (PMID 33776561, 2021). "In mild-grade CLP, clopidogrel- and vehicle-treated mice did not display a significant decrease in MAP, while thrombocytopenia and plasma concentrations of TNFα, IL6, IL10, MPO, TAT and organ damage reached similar levels in both groups, although lower than those reached in the high grade CLP." (PMID 34447900, 2021). "In our study, upon analyzing cytokine levels among patients with varying intensity of thrombocytopenia, the IL-6 levels did not change significantly during mild and moderate thrombocytopenia but were found to be decreased during ST in patients with P. vivax and P. falciparum infections." (PMID 31110658, 2019). "In particular, the IL-6-promoted megakaryocyte maturation in the absence of other added growth factors, which leads to elevated platelet production is an important focus when contemplating its implications on chemotherapy-induced thrombocytopenia." (PMID 22236378, 2012). "For this reason, we used the hyper-IL-6-encoding VACV strain GLV-1h90 in combination therapy with the chemotherapeutic agent mitomycin C. This approach improves therapeutic outcomes and reduces negative side effects such as thrombocytopenia." (PMID 22236378, 2012). "Similarly, there was a positive correlation with inflammatory markers, CRP and IL-6, and creatinine and a negative correlation with platelet count, indicative of a rising inflammation, a worsening kidney function, and thrombocytopenia, potentially attributable to worsening HIV and general condition." (PMID 39998057, 2025). "The degree of thrombocytopenia and hemoconcentration was similar in WT and CCR2–/– mice, but levels of IL-6 and IFN-γ, but not TNF-α, were decreased systemically in infected CCR2–/– mice." (PMID 21206747, 2010). "The AnxA1 mimetic significantly reduced thrombocytopenia and haemoconcentration in response to DENV infection and displayed efficacy on controlling innate immunity mediators, with more significant effects in spleen values rather than plasma levels for CCL5 and IL-6." (PMID 35293862, 2022).
bacteremia (158 papers, 2007 to 2026). "ARDS caused by bacterial sepsis is distinguished by its rapid onset, increased inflammatory markers (e.g. IL-6 and Procalcitonin [PCT]), and reduced systemic blood flow, often resulting in a more severe cytokine storm." (PMID 40761632, 2025). "The authors concluded that IL-6 was the best predictor for identifying patients at risk of bacteremia or prolonged fever episodes, outperforming both IL-8 and CRP in diagnostic accuracy." (PMID 40647525, 2025). "Numerous studies have demonstrated a strong association between elevated IL-6 levels and adverse outcomes in bacterial sepsis, including multi-organ dysfunction and mortality." (PMID 40647525, 2025). "Mice that received IL-6 neutralizing antibodies had significantly prolonged survival time and increased survival rates, suggesting that P. multocida bacteremia causes host death by inducing a cytokine storm." (PMID 38589976, 2024). "The cytokine pattern of IL-6/IL-10 has more remarkable diagnostic precision in bacteremia and severe infection in children with hematological tumors than PCT." (PMID 35463642, 2022). "The ROC curve was employed to further evaluate the diagnostic ability of body temperature, CRP, PCT, IL-6, and IL-8 in cases with respiratory bacterial infection and bacteremia." (PMID 35463642, 2022). "In bacteremia, PSMs together with Hla are able to cause a systemic increase in the concentration of IL-6, which is an activator of osteoclasts and facilitates the destructive bone resorption by increasing the number and activity of osteoclasts." (PMID 36555727, 2022). "Since 2017 we have been using procalcitonin and IL‐6, both having higher a diagnostic power for determining bacterial sepsis in children compared to CRP." (PMID 33108806, 2021). "Others have reported that complicated SAB is associated with significantly higher baseline IL-6 levels compared to uncomplicated bacteremia." (PMID 33820537, 2021). "A significant increase of IL-6 alone was associated with ADV-viremia and significant increases of IL-6 and IL-8 with bacteremia." (PMID 26315105, 2015). "Associations were found between the CC genotype of IL6 SNP rs1800795 and occurrence of bacteremia and between TLR5 SNP rs5744168 and protection from UTI." (PMID 25807366, 2015). "We found one polymorphism, the IL6 SNP rs1800795, specifically the CC genotype, to be associated with development of bacteremia." (PMID 25807366, 2015). "Elevated bacteremia in WT mice resulted in enhanced systemic inflammation as determined by plasma IL-6 measurements, compared to TREM-2 deficient mice." (PMID 24945405, 2014). "Controlling the intracellular response to IL-6 by promoting the required signaling arm and limiting unnecessary responses (e.g., antiviral genes in response to bacteremia) is a promising therapeutic avenue to reduce the risk of multiorgan dysfunction without impeding pathogen clearance." (PMID 40956626, 2025). "Increased levels of IL-6, IL-8 and TNFα have been shown to be significantly increased in S. aureus patients compared to healthy controls and are associated with a complicated course of infection in S. aureus bacteremia patients." (PMID 36969151, 2023). "Bacteremia may also cause high levels of inflammation in the serum and intestines and increased levels of inflammatory factors (IL-6, IFN-γ) (Michielan and D’incà, 2015)." (PMID 35071031, 2021). "TLR2 downregulation and IL-6 and IL-10 concentrations suggestive of immune dysregulation during early bacteremia may be associated with mortality from SAB." (PMID 33256638, 2020). "Furthermore, a strong release of TNF-α and IL-6 into the blood was associated with bacteremia." (PMID 38675794, 2024). "Finally, high levels of IL-6 in the sera has been associated with increased bacterial loads in melioidosis patients, and is also associated with a negative outcome and proposed as a diagnostic marker in generalized bacterial sepsis." (PMID 25503969, 2014).
bacteremia (continued). "In addition, previous studies indicated that the plasma level of IL-6 correlated with mortality in septic patients, and plasma levels of IL-6 might be used as a diagnostic marker for the presence of bacteremia." (PMID 23431240, 2013). "We used this concentration to mimic the physiological conditions of cytokine levels in the serum of patients with bacteremia, where the levels of IL-6 and IL-8 can reach several ng/ml and the level of TNFα can reach 1 ng/ml." (PMID 40540014, 2025). "Evidence has confirmed that IL-6 cannot predict bacteremia due to the low sensitivity and PPV values." (PMID 40046191, 2025). "The study emphasized PCT’s reliability for serial monitoring but cautioned about small sample size (16 bacteremia) and IL-6’s detection limits (max 300 pg/mL)." (PMID 40647525, 2025). "IL-6 showed 74% sensitivity and 49% specificity for bacteremia, with 45% positive predictive value, but correlated poorly with early CRP (r = 0.26 on day 1 vs. 0.53 on day 2)." (PMID 40647525, 2025). "The highest median IL-6 value within the first 48 h of ICU stay was significantly higher in bacterial sepsis than in viral sepsis (1848.00 ng/L [382.00–20,961.00] vs. 188.00 ng/L [84.90–540.00]; p < 0.001)." (PMID 41472286, 2025). "During the first days in the ICU, IL-6 levels were significantly higher in the bacterial sepsis group compared to the viral sepsis group." (PMID 41472286, 2025). "have found that IL‐6 is the best predictor of bacteremia and severe bacterial infection, with high sensitivity and specificity (90% and 85%, respectively)." (PMID 38967137, 2024). "According to the study, bacteremia was associated with a large increase in both IL-6 and IL-8, whereas ADV-viremia was associated with a significant increase in IL-6 alone." (PMID 39289412, 2024). "Four studies focused on the diagnostic value and the utilization of serum PCT, C-reactive protein (CRP), serum lactate, and Il-6 in predicting bacteremia in adult patients and diagnosis of bacterial sepsis." (PMID 38254218, 2024). "Released within 2 h after the onset of bacteremia, the levels of pro-inflammatory cytokine Interleukin-6 (IL-6) increase earlier than both PCT and CRP in neonatal septic patients." (PMID 38671704, 2024). "Evidence has confirmed that IL‐6 cannot predict but can exclude bacteremia due to the low sensitivity and PPV values." (PMID 38967137, 2024). "Our findings demonstrate that interrupting splanchnic nerve activity in established bacteremia is safe for blood pressure control, increases circulating IL-6 levels, expedites the clearance of bacteria from the bloodstream and improves the clinical state." (PMID 37535121, 2023). "IL6 was found to be significantly higher in the bacteremia group at T0 (p = 0.022) as well, being a moderately accurate test in predicting bacteremia (AUC = 0.748), but not at T1 (p = 0.574)." (PMID 37081067, 2023). "Several studies highlighted the importance of circulating IL-6 as a beneficial readout in diagnosing bacteremia." (PMID 38313162, 2023). "Further analysis showed that IL-6 and IL-8 are the cytokines that predict respiratory infection alone and respiratory infection with bacteremia." (PMID 35463642, 2022). "Among the 102 patients with completely normal CRP and PCT levels but high IL-6 levels (≥100 pg/mL), infectious diseases and bacteremia or fungemia occurred in 36 (35.3%) and 9 (8.8%) patients, respectively, until discharge (median HD of 5 days)." (PMID 36555941, 2022). "The outcomes illustrated that the levels of body temperature, CRP, PCT, IL-6 and IL-8 in bacteremia patients were 38.4°C, 93.7 mg/L, 0.79 ng/mL, 145.00 pg/mL and 34.6 pg/mL, respectively." (PMID 35463642, 2022). "A study published in 2004 proved that PCT and IL-6 were more reliable markers than CRP in predicting bacteremia in patients with febrile neutropenic fever." (PMID 34828740, 2021). "IL-6 and IL-1-beta concentrations were both significantly higher on day 1 in bacterial sepsis compared with SARS-CoV-2." (PMID 34956225, 2021).
bacteremia (continued). "The present data showed IL-17A and IL-6 were significantly increased in candidemia patients compared to both bacteremia patients and normal healthy controls." (PMID 34684298, 2021). "Its elevation in bacteremia is mainly due to regulation by IL‐6 or lipopolysaccharide through the JAK/STAT pathway." (PMID 34331328, 2021). "Two of three pigs with pronounced bacteremia showed an increase in serum IL-6: individual H7 showed an IL-6 peak of 1.9 ng/mL at 16 hpi, and individual H2 a peak of 0.9 ng/mL at 19 hpi." (PMID 31947746, 2020). "Continuous hemofiltration significantly decreases the serum levels of TBIL, DBIL, TBA, Lac, ammonia, TNF-α, IL-6, and improves 28-day mortality of patients with bacterial sepsis complicated by liver dysfunction." (PMID 30098593, 2018). "On the other hand, treatments with the ER-β selective agonist, WAY-202196, exert a protective effect in both male and female rodents subjected to CLP by decreasing TNF-α and IL-6 levels, reducing bacteremia, and maintaining intestinal integrity." (PMID 29925409, 2018). "It was found that the fungal sepsis is associated with substantial increase in all cytokines levels (TNF-α, IL-1β, IL-4, IL-6, and IL-10), when compared with bacterial sepsis." (PMID 28367457, 2017). "This study was conducted prospectively to evaluate the potential of interleukin (IL)-6, IL-8, and IL-10 for predicting bacteremia and to compare the levels of IL-6, IL-8, and IL-10 between patients during infection and patients after treatment." (PMID 28148470, 2017). "For instance, it has been shown that fungal sepsis in neonates is associated with substantial increase in IL-6 and TNF-α levels, when compared with bacterial sepsis." (PMID 28367457, 2017). "Thus, the hypothesis that nonsurgical periodontal therapy might reduce the bacterial load and associated bacteremia, therefore reducing the inflammatory stress during pregnancy and IL-6 cascade, contributes to reduction in CRP levels and, consequently, the incidence of APO." (PMID 29017560, 2017). "The presence of bacteremia was associated with low concentrations of HGF (p = 0.005), IL-15 (p = 0.002), IL-6 (p = 0.05), IP-10 (p = 0.008), MIG (p = 0.03) and MIP-1α (p = 0.03)." (PMID 28628613, 2017). "Consistently, in multi-marker analysis we found that the most relevant markers associated with presence of bacteremia were HGF, IL-15, IL-6, IP-10, MIG and MIP-1-α and additionally, G-CSF, IFN-γ, RANTES." (PMID 28628613, 2017). "In mice with severe infections (E. coli O4 107 cfu/mouse injected), Hx was increased by day 1 and remained above baseline despite high bacteremia and high levels of IL-6." (PMID 25888135, 2015). "In all 5 (10.42 %) of the 61 patients diagnosed with bacteremia, a significant increase of IL-6 (P < 0.0001) and IL-8 (P = 0.0006) was observed." (PMID 26315105, 2015). "We found that levels of IL-6 were positively correlated with the bacteremia as shown in other studies." (PMID 25888135, 2015). "After Bonferroni correction (adjusted α = 0.0083) the decrease of IL-6 between bacteremia and viremia (P = 0.0094) and between bacteremia and fungemia, (P = 0.0194) was not significant." (PMID 26315105, 2015). "Nonetheless, it is unlikely that bacteremia resulted in immune activation and IL-6 induction as only 2 of 7 rats showed bacteremia after 8 days of chronic total sleep deprivation." (PMID 23637783, 2013). "Mice deficient in the expression of CD40 have been shown to have improved survival during bacterial sepsis as a result of decreased induction of IL-6, IL-10, IL-12 and IFNγ expression." (PMID 21949840, 2011). "Compared with controls, the levels of IL-6, IL-8, IL-9, IL-15, IL-17, IP-10 and TNFα were significantly elevated in the bacterial sepsis-ARDS group." (PMID 21062445, 2010). "The low triglycerides we observe also contrast with the profile of bacterial sepsis in which high liver IL-6 coincides with high triglycerides." (PMID 19216742, 2009).
bacteremia (continued). "In predicting bacteremia or severe bacterial infection, IL-6 was the best predictor with the optimum IL-6 cut-off level of 42 pg/ml showing a high sensitivity (90%) and specificity (85%)." (PMID 18321393, 2008). "In predicting bacteremia or severe bacterial infection, the optimum IL-6 cut-off level was 42 pg/ml with a high sensitivity (90%) and specificity (85%), the positive predictive value was 94%." (PMID 18321393, 2008). "A prospective study was performed to assess the potential value of IL-6, IL-8 and C-reactive protein serum levels to predict severe bacterial infection or bacteremia in febrile neutropenic children with cancer during chemotherapy." (PMID 18321393, 2008). "Accumulating evidence suggest that peri-implant inflammation can contribute to a sustained systemic low-grade inflammatory state characterized by elevated inflammatory mediators, like interleukin (IL)-6 and C reactive protein, episodic bacteremia, and metabolic alterations." (PMID 41867638, 2026). "Furthermore, when the presence of bacteremia was included as an additional criterion, the IL-6 and CRP combination reached a sensitivity of 84%; however, the specificity remained considerably low at 34%." (PMID 41011807, 2025). "FluA triggers a rapid activation of the innate immune pathways, such as NF-κB and STAT1/3, leading to an early and intense surge in proinflammatory cytokines, including TNF-α, IL-6, and IL-1β, that surpasses both the speed and magnitude of responses observed in bacterial sepsis." (PMID 41321454, 2025). "The close mechanistic relationship between IL-6 and MIP-3α may support the use of the latter as a diagnostic biomarker for certain types of bacterial sepsis." (PMID 38672079, 2024). "IL-6 ≥ 18.79 pg/mL indicated the presence of a pulmonary bacterial infection in patients, whereas IL-6 ≥102.6 pg/mL may suggest pulmonary bacterial infection with bacteremia." (PMID 39559703, 2024). "It is controversial of IL‐6 clinical in bacteremia patients with FN." (PMID 38967137, 2024). "(2016) analyzed 3023 samples (2819 fever case samples and 204 control samples) and found that the positivity rates of interleukin-6 (IL-6) and IL-10 in children with bacteremia were 92.8% and 82.2%, respectively, which were higher than those of PCT (33.8%) and CRP (73.1%)." (PMID 39559703, 2024). "IL6, on the other side, might be a useful biomarker in that, being higher in the bacteremia group at T0, with a sensitivity identical to that of PCT." (PMID 37081067, 2023). "A subgroup analysis stratified by survival status among those with bacteremia demonstrated that patients who died within 28 days had a significantly higher level of IL-6, a higher rate of use of antifungal drugs, and a longer duration of mechanical ventilation (all p ≤ 0.05)." (PMID 37768395, 2023). "From 25-to-30-h of bacteremia, IL-6 levels remained consistently elevated in the sham group." (PMID 37535121, 2023). "At 23-h of bacteremia, prior to splanchnic denervation, there were similar increases in the plasma concentrations of the pro-inflammatory cytokine, IL-6, in the sham (from 2.84 ± 0.23 to 4.42 ± 0.706 ng/mL, P = 0.049) and intervention groups, (3.46 ± 0.74 to 5.20 ± 0.76 ng/mL, P = 0.027)." (PMID 37535121, 2023). "When IL-6 ≥ 18.79 pg/ml may suggest pulmonary bacterial infection, while IL-6 ≥ 102.6pg/ml may suggest pulmonary bacterial infection with bacteremia." (PMID 35463642, 2022). "In patients with bacteremia, IL-6 was the first to increase, followed by PCT and CRP." (PMID 36555941, 2022). "IL-6 ≥18.79pg/mL indicates the presence of pulmonary bacterial infection in newly diagnosed NHL patients, and IL-6 ≥102.6pg/mL may suggest pulmonary bacterial infection with bacteremia." (PMID 35463642, 2022). "In newly diagnosed NHL patients, IL-6 ≥18.79pg/mL could indicate the existence of pulmonary bacterial infection while IL-6 ≥102.6pg/mL may suggest pulmonary bacterial infection with bacteremia." (PMID 35463642, 2022).